ENSG00000267140 (novel protein)
Gene: Protein-coding gene on chromosome 18 (35,443,871 to 35,497,940, reverse strand). Ensembl gene ENSG00000267140.
Genetic constraint (gnomAD): Loss-of-function variants: 3 observed, 2.94 expected, observed/expected ratio (o/e) 1.02, 90% interval 0.44 to 1.86. That is too few expected variants to judge how well the gene tolerates losing a copy. Missense variants: 88 observed, 71.36 expected, observed/expected ratio (o/e) 1.23, 90% interval 1.04 to 1.47. Synonymous variants: 37 observed, 30.85 expected, observed/expected ratio (o/e) 1.2, 90% interval 0.92 to 1.58.